RNF43 (ring finger protein 43)
Diseases named in the same sentence as RNF43 in open-access papers (continued):
Sharing a sentence is not in itself a finding about the gene and the disease.
liver cancer (6 papers, 2014 to 2025). An epithelial or non-epithelial malignant neoplasm that arises from the liver. "In humans, mutation of RNF43 increases the risk of liver diseases such as fatty liver disease and liver cancer, as well as reduces the life expectancy of patients." (PMID 38965537, 2024). "Here we find that loss of RNF43/ZNRF3 predisposes to liver cancer by controlling liver lipid metabolic ground-state and the balance between proliferation/differentiation in hepatocytes." (PMID 35039505, 2022). "RNF43 mutations have been discovered in various human cancers including colon, pancreatic, stomach, ovarian, and liver cancers." (PMID 35487932, 2022). "Here, the authors show that RNF43/ZNRF3 alterations predispose to liver cancer by controlling the differentiation and lipid metabolic state of hepatocytes." (PMID 35039505, 2022). "Our observations imply that RNF43/ZNRF3 predispose to liver cancer, at least in part, by altering the hepatocyte metabolic ground-state while, in parallel, preventing the tissue from completely regenerating upon damage." (PMID 35039505, 2022). "Upon injury, Rnf43/Znrf3 deletion results in defective hepatocyte regeneration and liver cancer, caused by an imbalance between differentiation/proliferation." (PMID 35039505, 2022). "We next performed differential expression analysis of the livers of patients harbouring WNT mutations (WNT), RNF43 and ZNRF3 (R&Z) and RNF43 or ZNRF3 (RorZ) compared to liver cancer patients with WT alleles for these." (PMID 35039505, 2022). "Our results imply that RNF43/ZNRF3 predispose to liver cancer by controlling the proliferative/differentiation and lipid metabolic state of hepatocytes." (PMID 35039505, 2022). "Some RNF43 mutations cause loss of function, promote β-catenin stabilization, and induce tumorigenesis; RNF43 mutations are frequently observed in gastric, ovarian, pancreatic, endometrial, colon, and liver cancers." (PMID 41487817, 2025). "To determine the relevance of our findings in human liver cancer, we next assessed the effect of RNF43/ZNRF3 mutations in human primary liver tumours taking advantage that the projects LIRI-JP and LICA_FR from the ICGC collection, contained genomic and expression data of the same tumours." (PMID 35039505, 2022). "For example, using such antibodies RNF43 protein was observed to be over-expressed in liver cancers, lost in a subset of gastric and colorectal tumors, and to correlate with gastric and clear cell renal cancer patient survival." (PMID 37023034, 2023). "In summary, our studies provide a framework to start to understand the role of the tumour suppressors RNF43/ZNRF3 in liver cancer." (PMID 35039505, 2022). "Our findings might aid on the management of those RNF43/ZNRF3 mutated individuals at risk of developing fatty liver and/or liver cancer." (PMID 35039505, 2022). "In summary, our results indicated that human liver cancer patients bearing ZNRF3 and/or RNF43 mutations present altered liver lipid metabolism, in agreement with our findings in the Rnf43/Znrf3 mutant mouse model, and identified ZNRF3 and/or RNF43 as potential prognostic biomarkers for liver cancer." (PMID 35039505, 2022). "However, the effect of negative feedback by the enhanced expression of RNF43 has not been clarified in colorectal or liver cancer." (PMID 24466159, 2014).
melanoma (6 papers, 2021 to 2025). A malignant, usually aggressive tumor composed of atypical, neoplastic melanocytes. "Ultimately, RNF43 overexpression here efficiently suppressed all tested pro-metastatic properties of melanoma cells associated with WNT5A and its (co)receptors." (PMID 34702444, 2021). "Similarly, RNF43‐mutated UACC‐257 melanoma cells showed higher sensitivity to MEK inhibitors than Mel1617 cells expressing wild‐type RNF43." (PMID 38225722, 2024). "RNF43 overexpression abrogates the Wnt5A-induced drug resistance and tumor progression and improves the OS in patients with melanoma." (PMID 41487817, 2025). "Surprisingly, R2PD1 caused 50% to 90% PD-L1 degradation in melanoma cell lines, which was dependent on ZNRF3/RNF43." (PMID 38638430, 2024). "In melanoma, RNF43 has been found to inhibit cell invasion and reverse the resistance to BRAF V600E and MEK inhibitors by stimulating the ubiquitination and proteasomal degradation of VANGL2 and inhibiting ROR2 in vitro and in vivo." (PMID 37848933, 2023). "In conclusion, the dose-dependent effect mediated by RNF43 showed the features of the onco-suppression in melanoma in vivo model." (PMID 34702444, 2021). "Elevated expression of WNT5A associates with negative overall survival in melanoma; we have observed an inverse correlation for RNF43, which was a positive prognostic factor in melanoma and got silenced as melanoma progressed." (PMID 34702444, 2021). "Further, we show that RNF43 is a relevant inhibitor of pro-metastatic WNT5A signaling in melanoma where it prevents both WNT5A-induced invasive behavior and WNT5A-assisted development of resistance to B-RAF and MEK inhibitors." (PMID 34702444, 2021). "All these assays strongly support the conclusion that RNF43 acts as a strong molecular inhibitor of WNT5A-triggered proinvasive features of melanoma." (PMID 34702444, 2021). "(A, B) RNF43 expression is lower in melanoma when compared with the skin and benign melanocytic skin nevus (A) and in the case of distant metastasis compared to the primary tumors (B), unpaired two-tailed t-test: ****p<0.0001." (PMID 34702444, 2021). "Causes PD-L1 degradation in melanoma cells, which is dependent on ZNRF3/RNF43." (PMID 38638430, 2024). "RNF43 inhibits WNT5A-dependent invasive properties of human melanoma." (PMID 34702444, 2021). "Importantly, analysis of other datasets showed that RNF43 low melanoma patients have shorter overall survival (OS)." (PMID 34702444, 2021). "Interestingly, the expression of two genes encoding direct targets ubiquitinated by RNF43, namely, DVL3 and VANGL1, increased during melanoma progression and high expression in both cases correlates with bad prognosis and shorter overall survival." (PMID 34702444, 2021). "Lower proliferation of RNF43/ZNRF3 dKO cells can be caused by senescence because these cells have elevated WNT5A pathway activity (i.e.) and WNT5A at the same time causes a senescence-like phenotype of melanoma after exposition to vemurafenib." (PMID 34702444, 2021). "Thus, we aimed to detect the differences in mechanisms behind targeted therapies resistance acquisition to characterize better the function of RNF43 in melanoma." (PMID 34702444, 2021). "All these findings are in line with the hypothesis that RNF43 acts in melanoma as a tumor suppressor that restricts WNT5A-induced biological processes and gets silenced during melanoma progression." (PMID 34702444, 2021). "Alternatively, RNF43/ZNRF3 KO could affect also canonical Wnt/β-catenin pathway that was shown to drive distinct features of melanoma cells than the ones related to the WNT5A-specific events." (PMID 34702444, 2021). "Next, RNF43 acted as melanoma suppressor and improved response to targeted therapies in vivo." (PMID 34702444, 2021). "From the other angle, the low RNF43 expression might be explored as a marker of resistant melanoma phenotype." (PMID 34702444, 2021). "RNF43 inhibits melanoma proliferation and response to vemurafenib in vivo." (PMID 34702444, 2021).
melanoma (continued). "Moreover, we show that RNF43 could be a negative regulator of melanoma phenotype plasticity by targeting MITF-low/WNT5A-high melanoma cells." (PMID 34702444, 2021). "These activities of RNF43 are physiologically relevant and block pro-metastatic WNT5A signaling in melanoma." (PMID 34702444, 2021). "RNF43 inhibits responses to WNT5A, which results in the suppression of invasive properties of melanoma cells." (PMID 34702444, 2021). "(C, D) RNF43 expression is a negative prognostic factor in melanoma." (PMID 34702444, 2021). "RNF43-overexpressing melanoma cells do not develop resistance to BRAF V600E targeted therapies." (PMID 34702444, 2021).
serrated polyposis (6 papers, 2021 to 2023). "The RNF43-associated serrated polyposis is a genetic disorder characterized by serrated polyposis (5–100 polyps) and an increased risk of CRC, not precisely estimated." (PMID 36768460, 2023). "Its inactivation has been reported not only as a somatic event in tumors, but also as a germline alteration identified in a number of cases of serrated polyposis syndrome, thus defined as RNF43-associated serrated polyposis cases." (PMID 35075588, 2022). "RNF43 is not included in the polyposis gene panel in Oxford, but sequencing was performed due to a family history of serrated polyposis and an RNF43 variant." (PMID 35128723, 2022). "However, there is no strong link between RNF43 mutation and serrated polyposis, with a prevalence of only 1.5–2.5% among SPS patients." (PMID 35128723, 2022).
cyst (5 papers, 2017 to 2023). A sac-like closed membranous structure that may be empty or contain fluid or amorphous material. "Mutated KRAS and RNF43 detected from tumors, cyst fluid, pancreatic juice, and blood cell‐free DNA may serve as novel biomarkers of advanced neoplasia in the molecular surveillance and stratification for IPMN patients." (PMID 35229994, 2022). "While in the absence of oncogenic KRAS solely RNF43 loss increased cyst size, its presence ascribed in both RNF43 and PTEN knockdown organoids a more cystic growth pattern compared to scramble controls." (PMID 31236113, 2019).
gastric adenocarcinoma (5 papers, 2018 to 2025). "RNF43 was found to be frequently mutated in tumors with microsatellite instability and was identified as a significantly mutated driver gene in gastric adenocarcinoma." (PMID 36439494, 2022). "Furthermore, mutations in KMT2D, ERBB2/3, and RNF43 are also observed in both G-EAC and gastric adenocarcinoma." (PMID 40432921, 2025).
lung adenocarcinoma (5 papers, 2021 to 2023). A carcinoma that arises from the lung and is characterized by the presence of malignant glandular epithelial cells. "Previous studies have found that the overexpression of RNF43 can directly ubiquitinate E-cadherin, leading to its degradation and thus potentiating metastasis of lung adenocarcinoma through inducible epithelial-to-mesenchymal transition (EMT)." (PMID 37848933, 2023). "However, a recent study demonstrated that RNF43 facilitates the epithelial-mesenchymal transition (EMT) of lung adenocarcinoma through the ubiquitination and degradation of phosphorylated E-cadherin by activated c-Src." (PMID 37304674, 2021). "We tested an alternative lung adenocarcinoma cell line, H3122, and inhibiting MET with Crizotinib reduced mature LRP6, an effect that was almost abolished when ZNRF3/RNF43 where siRNA-inhibited." (PMID 34590584, 2021). "Our previous data demonstrated that RNF43 was able to ubiquitinate and degrade E-cadherin phosphorylated by c-Src to facilitate the EMT process in lung adenocarcinoma, indicating the mechanism that activated c-Src induced the EMT phenotype." (PMID 34367939, 2021). "Similarly, RING finger protein 43 (RNF43) also ubiquitinates E-cadherin upon c-Scr activating E-cadherin and promotes EMT progression n lung adenocarcinoma." (PMID 33466790, 2021).
metastatic colorectal cancer (5 papers, 2021 to 2025). "This phase Ib dose-­escalation study evaluated the maximum tolerated dose of WNT974 in combination with encorafenib and cetuximab in patients with BRAF V600E-mutant metastatic colorectal cancer with RNF43 mutations or RSPO fusions." (PMID 36811382, 2023). "Microsatellite-stable BRAF-mutated metastatic colorectal cancer patients treated with anti-EGFR/BRAF combinations had better responses and survival outcomes when RNF43 was mutated compared with wild-type cases." (PMID 39452477, 2024). "RNF43, a WNT signaling pathway negative regulator, can predict the response of BRAF V600E MSS metastatic colorectal cancer against BRAF/EGFR combination therapy, where MSI-H always carries RNF43 wildtype-like, encoding p.G659fs* and presents an intermediate response frequency." (PMID 40860811, 2025). "A phase I clinical trial of a peptide vaccine ring finger protein 43 (RNF43) and Tomm34 combined with uracil‐tegafur (UFT)/LV for patients with metastatic colorectal cancer has been done in Japan, including the safety and immunological responsiveness of this combination therapy." (PMID 34257607, 2021).
Pancreatic cysts (5 papers, 2016 to 2022). A cyst of the pancreas that possess a lining of mucous epithelium. "Previous studies have found RNF43 to be functionally mutated in pancreatic cysts and mucinous ovarian cancer." (PMID 27661107, 2016). "Pancreatic Rnf43 knockout and Kras activated mice (Rnf43−/−; KrasG12D) develop from pancreatic cysts to pancreatic ductal adenocarcinoma which can be blunted by suppression of Wnt/β‐catenin signaling pathway." (PMID 35229994, 2022). "As deficient RNF43 caused bigger pancreata without obvious alterations of pancreas architecture, deficiency of RNF43 alone is not sufficient to cause pancreatic cysts." (PMID 35229994, 2022).
cholangiocarcinoma (4 papers, 2017 to 2023). A carcinoma that arises from the intrahepatic biliary tree (intrahepatic cholangiocarcinoma) or from the junction, or adjacent to the junction, of the right and left hepatic ducts (hilar cholangiocarcinoma). "The activation of Wnt signaling has been detected in cholangiocarcinoma, and the validated mutations identified so far are an inhibitory ring finger protein 43 (RNF43) mutation, overexpression of Wntless, and hypermethylation of secreted frizzled-related protein 2 (SFRP2)." (PMID 31684152, 2019). "Of note, neither GNAS nor RNF43 mutations, which arose in cholangiocarcinoma as reported, were found in our samples." (PMID 28008139, 2017).
clear cell renal cell carcinoma (4 papers, 2021 to 2023). "In clear cell renal cell carcinoma, RNF43 can inhibit malignant behavior and reverse pazopanib resistance by inhibiting the YAP signaling by decreasing YAP phosphorylation via p-LATS1/2." (PMID 37848933, 2023).
glioma (4 papers, 2016 to 2025). A benign or malignant brain and spinal cord tumor that arises from glial cells (astrocytes, oligodendrocytes, ependymal cells). "Notably, RNF43 expression is related to OS, possibly serving as a prognostic predictor for patients with glioma." (PMID 41487817, 2025).
invasive carcinoma (4 papers, 2020 to 2025). A carcinoma that is not confined to the epithelium, and has spread to the surrounding stroma. "Of note, we observed a significant increase in the frequency of RNF43 mutations from low-grade to high-grade IPMNs associated or concomitant with invasive carcinoma (trend test, P = 0.01)." (PMID 36454217, 2023). "Mutations in SMAD4 and TGFBR2 are frequently restricted to invasive carcinoma, while RNF43 alterations are largely in non-invasive lesions." (PMID 32796935, 2020). "RNF43-mutated caused invasive CRC by aggravating and perpetuating inflammation due to impaired epithelial barrier integrity and pathogen control, and RNF43 inactivated mutation was even sufficient to cause spontaneous intestinal inflammation, resulting in subsequent invasive carcinoma development." (PMID 40860811, 2025). "However, RNF43 does not seem to be involved in the progression to invasive carcinoma but it plays a role in the transition from low to high dysplasia." (PMID 34884643, 2021).
lung carcinoma (4 papers, 2019 to 2025). "The RNF43 gene is often mutated in various types of cancers, including lung cancer." (PMID 40735046, 2025). "To delve deeper into the specific role of RNF43 mutations in lung cancer and their relevance to therapy response, we provide the first report of marked efficacy of the dabrafenib and trametinib therapeutic combination in a patient with MSS NSCLC with BRAFV600 and RNF43 mutations." (PMID 40735046, 2025). "We successfully identified epistasis in RGL1:RAD51B in ALL and NSCLC lung cancer, SYNE1:RNF43 in ADE and FHIT:TSPAN8 in SQC risk development." (PMID 30956756, 2019). "Interestingly, all the three significant epistasis—-RGL1:RAD51B in ALL and NSCLC lung cancer, SYNE1:RNF43 in ADE and FHIT:TSPAN8 in SQC risk development—-were displayed as interaction between networks." (PMID 30956756, 2019). "Previously, we showed that LGR4 was highly expressed in the lung cancer cell line A549 and RNA-seq expression data showed no expression of LGR5, LGR6, RNF43, and ZNRF3 in A549 cells." (PMID 37402772, 2023).
polyposis (4 papers, 2022 to 2026). "The results highlight the complexity of genetic counseling in RNF43 positive families– particularly in families without polyposis." (PMID 39546056, 2024). "Of note, neither RNF43 nor CHEK2 is included in the current UK Cancer Genetics Group panel testing for polyposis patients." (PMID 35128723, 2022).
inflammatory bowel disease (3 papers, 2021 to 2025). A spectrum of small and large bowel inflammatory diseases of unknown etiology. "RNF43 is also somatically mutated in 11% of CACs that have been linked with chronic inflammation and long-lasting inflammatory bowel disease (IBD)." (PMID 34488905, 2021). "Furthermore, analyses of inflammatory bowel disease (IBD)-associated CRCs have noted an association between chronic inflammation and somatic RNF43 variants and mucinous or signet-ring cell histological subtypes." (PMID 38725616, 2024).
Lynch syndrome (3 papers, 2022 to 2025). An autosomal dominant hereditary neoplastic syndrome characterized by the development of colorectal carcinoma and a high risk of developing endometrial carcinoma, gastric carcinoma, ovarian carcinoma, renal pelvis carcinoma, and small intestinal carcinoma. "Despite the shared dMMR phenotype between RNF43 mutations and Lynch syndrome, we could not identify any RNF43 mutations in the Lynch syndrome dMMR cancers." (PMID 35907983, 2022).
metastatic disease (3 papers, 2023 to 2025). "Concomitant RNF43 mutation in metastatic disease, was associated with a significantly higher incidence of disease control from combined BRAF and EGFR inhibition, when compared to those without an RNF43 mutation (100% vs. 54%, p = 0.02)." (PMID 41002577, 2025). "Where plasticity is restrained, such as in early metastatic disease, or through targeting ligand-dependent WNT pathway Rnf43 mutations, marked therapeutic responses are observed." (PMID 41286180, 2025). "Single nucleotide variant (SNV) frequencies of 34 candidate genes (including KMT2D (46.4%), ZFHX3 (33.3%), JAK1 (31.9%), and RNF43 (27.5%)) and 16 candidate genes (including KMT2D (33.3%) and JAK1 (28.3%)) were higher in MMR-d primary tumors and MMR-d metastatic tumors, respectively." (PMID 36675550, 2023).
mucinous ovarian cancer (3 papers, 2021 to 2024). An invasive malignant neoplasm that arises from the ovary and is characterized by the presence of malignant epithelial cells that contain intracytoplasmic mucin and may resemble the epithelial cells of the endocervix or gastrointestinal tract. "RNF43 is also a tumor suppressor gene in mucinous tumors of the ovary, and RNF43 mutation was found in 21% of mucinous ovarian carcinomas." (PMID 34488905, 2021).
ovarian mucinous tumor (3 papers, 2021 to 2025). "Given that RNF43 downregulates WNT signaling via targeted ubiquitin-dependent degradation of Frizzled receptors, loss-of-function mutations in RNF43 might promote ovarian mucinous tumor progression." (PMID 40697329, 2025).